IL10 (interleukin 10)
Diseases named in the same sentence as IL10 in open-access papers (continued):
Sharing a sentence is not in itself a finding about the gene and the disease.
breast cancer (continued). "Therefore, it is essential to conduct further follow-up studies to delve deeper into the impact of interleukins (IL-5, IL-7, IL-16, and IL-10) on the two subtypes of breast cancer (HER2-positive and HER2-negative)." (PMID 37910571, 2023). "Moreover, the abundance of Mucispirillum positively correlated with the concentration of the inflammatory suppressor IL‐10 in breast cancer model mice." (PMID 37647442, 2023). "Additionally, IL-10 (IVW-OR: 1.14, 95% CI: 1.03–1.26, P = 0.012) showed a suggestive association with an increased risk of HER2-negative breast cancer." (PMID 37910571, 2023). "Although understudied in breast cancer, mouse models and clinical trials in other solid tumours including renal cell carcinoma and melanoma have shown IL-10 inhibition upregulates anti-tumour CD8+ T cell responses and subsequently potentiates immunotherapy treatment." (PMID 36900307, 2023). "IL-1 and IL-10 are highly expressed in high grade breast cancer." (PMID 37340387, 2023). "Breast cancer cases may benefit from therapies that blockade the EZH2-CCL2/CCR2 cell revulsive axis or its amplifier IL-10-EGFR pathway for the alleviation of cancer growth and dissemination." (PMID 36038549, 2022). "Vitamin D3 has been predicted to prevent or alleviate breast cancer, and the effects may work through genes, such as IL10." (PMID 35150235, 2022). "Based on these finding, we hypothesized that sPD-L1 from breast cancer could increase the proportion of Bregs and IL-10 secretion and induce Treg differentiation and Teff exhaustion." (PMID 35935985, 2022). "In breast cancer, macrophages characterized by the expression of IL10 could hamper CD8+ T-cell-dependent responses by inhibiting IL-12 expression in intratumoral dendritic cells." (PMID 36439109, 2022). "Therefore, the high level of IL-4 and IL-10 expressing T cells in the spleen, as well as mLN at day 21, indicates systemic immune suppression at the late stage of breast cancer." (PMID 36232335, 2022). "In more than 50% of breast cancers, higher IL-10 expression was reported." (PMID 36544523, 2022). "In breast cancer, IL-10 secreted by macrophages could suppress interleukin- (IL-) 12 expressed in DCs and subsequently decrease pathologic complete response of cancer." (PMID 35127947, 2022). "Thus, our results indicate that IL-6- and IL-10-mediated neutrophil N2 conversion is a key mechanism to promote lung metastasis of breast cancer in the context of Lin28B expression." (PMID 35173168, 2022). "It is known that IL-10 protects from carcinogenic and improves tumor immune surveillance, besides inhibiting tumor migration and progression, particularly in the early stages of breast cancer." (PMID 35601827, 2022). "We observed increased IL10 immunostaining in breast cancer tissues versus normal breast tissue." (PMID 33500726, 2021). "There are also studies conducted on promoter methylation states of 100 genes, including BRCA1, CCND2, BCL2, MDR1, IL10, and TWIST, recorded to understand how alteration between hypermethylation and hypomethylation over time contributes to select breast cancer susceptibility biomarkers." (PMID 34576196, 2021). "We found significantly elevated serum IL10 in patients with breast cancer versus healthy subjects." (PMID 33500726, 2021). "Therefore, IL-10 in TME of breast cancer induces immunosuppression and assists the evasion from tumor immune surveillance, promoting tumor cell development and metastasis." (PMID 33957948, 2021). "Furthermore, the authors concluded that IL-10 suppresses aromatase expression in human breast adipose stromal cells and thereby moderates the aromatase-induced breast cancer progression." (PMID 34944905, 2021). "Thus, I used IL-10 and-15 as therapeutic agents in the 4T1 cell line, which is a mouse cell line of breast cancer, and the NXS2 cell line, which is a mouse cell line of neuroblastoma." (PMID 33912464, 2021).
breast cancer (continued). "Moreover, tumor-infiltrating NKs and MDSCs underwent transcriptional reprogramming and enhanced the IL-10 production via STAT3 in breast cancer." (PMID 33957948, 2021). "Likewise, HCMV IL-10 exposed MCF-7 human breast cancer cells showed a significant up-regulation of matrix metalloproteinase-10 (MMP-10) gene expression, thus promoting excessive proliferation and tissue invasion." (PMID 33937031, 2021). "Meanwhile, macrophages are confirmed as the primary source of IL-10 which inhibits the secretion of IL-12 by TIDCs to weaken the efficacy of CD8+ T cell-dependent chemotherapy in untreated mammary carcinomas by evaluating FACS-sorted epithelial versus stromal cell populations." (PMID 34625124, 2021). "IL-10 promotes breast cancer cell proliferation and metastasis via immunosuppression." (PMID 33003428, 2020). "We speculate that IL-10 expression in breast cancer may serve as a preferential metastatic condition that permits cells to evade host anticancer immunity, which is dependent on the ER and PR status." (PMID 33003428, 2020). "Our study suggests that the inhibition of MTDH and IL-10 may have potential with regard to developing new therapeutic strategies for breast cancer." (PMID 33003428, 2020). "Interestingly, high IL10 levels were also found in inflammatory breast cancer, a particularly aggressive and highly metastatic form of breast cancer, in which this cytokine correlates with the presence of lymphovascular invasion." (PMID 32300557, 2020). "In addition, it has been shown that IL-35 secreted by breast cancer cells also promotes the IL-10 production and sharply decreases the secretion of Th1-type cytokine IFN-γ and IL-17 in conventional T cells." (PMID 32849603, 2020). "Furthermore, distinct patterns of cytokines, including expression of IFN-γ, IL-4, and IL-10, have been observed in specific breast cancer groups compared to a healthy population." (PMID 32560316, 2020). "IL-10 exerts a complex role in breast cancer initiation and progression." (PMID 33312693, 2020). "In addition, IL-10 promoter hypomethylation and IL-10 overexpression were observed in breast cancer tumor tissues compared to normal breast tissue and benign breast tissue." (PMID 32582189, 2020). "Expression of IL-10 is higher in breast cancer patients than in healthy persons." (PMID 32380517, 2020). "Studies on the role of Il-10 in breast cancer showed contradicting results." (PMID 33297495, 2020). "Several studies have investigated the relationships between IL-10 polymorphisms and breast cancer risk, but have not completely clarified." (PMID 32380517, 2020). "We also assessed the expression of Ifn-γ, Il-6 and Il-10 in mammary tumors." (PMID 30640711, 2019). "Finally, only the high-grade CA1a human breast cancer cell conditioned media positively affected anti-inflammatory IL10 markers in both macrophages, while both CA1h and CA1a conditioned medias upregulated IL10 and downregulated TNFα in monocytes." (PMID 31105883, 2019). "A follow-up study with 534 patients demonstrated IL6, IL8, and IL10 may consider as indicators for poor prognosis and metastatic of breast cancer." (PMID 31398937, 2019). "A higher percentage of M2c cells, which produce higher levels of IL-10, may induce progression to advanced breast cancer stages." (PMID 29614988, 2018). "IL-10 acts as an anti-inflammatory molecule preventing tumor development in animal models of chronic inflammation-induced carcinogenesis, and inducing regression of established breast cancer metastases." (PMID 29721190, 2018). "And the chloroform ethanol extract of XHP could increase the expression of IL-2 in Walker 256 breast cancer cells, reduce expression of IL-10, and improve the proportion of T lymphocytes, thus playing antitumor effect." (PMID 29849718, 2018).
breast cancer (continued). "We have reported the diversity of polymorphism frequencies for the CYP2D6, CYP3A5, CYP2C8, and IL-10 genes in breast cancer patients from Mexico and Spain and classified them by metabolic activity for chemotherapy but no specific function has been described for these polimorphisms." (PMID 29997359, 2018). "In addition to the change in immune cell composition, elevated levels of immunosuppressive cytokines such as TGF‐β1, IL‐10, and GM‐CSF have been observed in the TDLNs of patients with breast cancer and other carcinoma diseases." (PMID 28993429, 2017). "We genotyped 100 premenopausal Eastern European (Lithuanian) patients with stage I-II breast cancer, ≤50 years old at the time of diagnosis, for interleukin 10 -592A > C, −819C > T and -1082A > G and tumor necrosis factor α -308G > A single nucleotide polymorphisms in the gene promoter region." (PMID 26112140, 2015). "According to our data, IL10 -1082A > G, −819 T > C, −592A > C polymorphisms and phased haplotypes have not revealed a prognostic value for breast cancer." (PMID 26112140, 2015). "Despite the fact that in earlier studies the −1082 G allele (which had also been related to higher IL10 expression) was associated with a lower breast cancer risk, it seems not to have a major impact on a further course of the disease in our study." (PMID 26112140, 2015). "As such, promoter hypomethylation of IL-10 activates its expression and inhibits the generation of immune response against breast cancer, while hypomethylation of the immunogenic antigen SPAN-Xb may result in de novo B-cell response in myeloma cells." (PMID 25860442, 2015). "Moreover, increased serum HDL-C is associated with greater production of anti-inflammatory cytokines such as interleukin 10, which thought to play a protective role against breast cancer." (PMID 26554382, 2015). "Furthermore, IL-10 has been found to act directly on breast cancer cells to promote survival in response to chemotherapy involving a STAT3/bcl-2 mechanism." (PMID 26106384, 2015). "In addition, we analyzed the presence of M1 (IL-12+) and M2 (IL-10+) macrophages in the mammary tumor microenvironment." (PMID 25599228, 2015). "IL-6 contributes to lung and breast cancer cell malignancy and effusion, and IL-6 and IL-10 may bias the induction of the immune response and lead to a state of tolerance against tumors." (PMID 25299052, 2014). "We analyzed not only the association of individual polymorphisms and breast cancer risk, but also the effects of combinations of functionally related polymorphisms (NFKB1 and NFKBIA; IL-8 and IL-10; and TNF c.-418 and c.-488), menopausal status, histopathological type, and cancer grading." (PMID 25559835, 2014). "To focus on cytokines and growth factors specifically produced by ASCs (EGF, FGF, HGF, SDF, IL6, IL8, IL10) or epithelial breast cancer cells (EGF, FGF, HGF) known to be relevant in tumorigenesis, we carried out Q-PCR analyses both on ASCs or primary breast cancer cells, before and after co-culture." (PMID 24327602, 2014). "NFKB1, NFKBIA, IL-8, IL-10, and TNF polymorphisms could serve as useful predictive biomarkers for breast cancer risk among women in East China." (PMID 25559835, 2014). "ILT4 and IL-10 may be cooperatively used as predictors of clinical outcomes in breast cancer patients." (PMID 24762057, 2014). "Based on previous work and our findings presented here, ILT4 expression in breast cancer may be regulated by IL-10 and promote lymph node metastasis by inducing TILs apoptosis and suppressing T-cell response." (PMID 24762057, 2014).
breast cancer (continued). "For example, the cancer immunotherapy trial network (CITN) has considered a pilot clinical trial testing the combination of topical imiquimod and IL-10 blockade in breast cancer patients with chest wall metastasis (per communication with Dr. Martin Cheever, CITN director)." (PMID 24624132, 2014). "In a recent review the role of IL-10 in breast cancer is discussed." (PMID 24138789, 2013). "Elevated serum level of IL-10 was observed in breast cancer patients." (PMID 24138789, 2013). "The fact that HCMV expresses a viral analogue of human IL-10 may lead to the conclusion that this could be one of the mechanisms of breast cancer promotion by the virus." (PMID 24138789, 2013). "This and the present study indicate that low levels of IL-10 may play a facilitative role in the development of breast cancer." (PMID 20553628, 2010). "Our findings suggest that IL-10 promoter polymorphisms participate in the progression of breast cancer rather than in its initial development in Chinese Han women." (PMID 20553628, 2010). "The main finding of our study suggests that IL-10 promoter polymorphisms participate in the progression of breast cancer rather than in its initial development." (PMID 20553628, 2010). "IL10 has been shown to have anti-metastatic and anti-tumour effects in murine breast cancer models." (PMID 16842617, 2006). "Polymorphisms within key interleukin genes (IL1A, IL1B, IL1RN, IL4R, IL6 and IL10 do not appear to play a significant overall role in breast cancer susceptibility or severity." (PMID 16842617, 2006). "The plasmatic levels of VEGF (breast cancer: range 31.2 – 177.9 pg ml−1; controls: 43.7 – 59.6), IL-10 (breast cancer: 20.9 – 31.1; controls: 16.9 – 21.7) and spermine (breast cancer: 0.25 – 4.05; controls: 0.66 – 2.51) did not significantly differ between groups." (PMID 14562018, 2003). "Although IL10 showed very low expression it may exert significant inhibition of T-cells in breast carcinoma." (PMID 11870535, 2002). "Although traditionally associated with highly proliferative characteristics through the secretion of IL-4, IL-6, and IL-10, which activate M2 macrophages, a recent study suggests that Th2 cells can directly block mammary carcinogenesis by inducing a terminal differentiation of breast cancer cells." (PMID 40136347, 2025). "Moreover, that study demonstrated a significant correlation between IL-10 positivity and lymph node metastasis; breast cancer patients with nodal metastases were more likely to have high IL-10 in their tumors than those without nodal spread (67% vs. 41%, p ≈ 0.04 in their cohort)." (PMID 41007766, 2025). "Genetic studies of the anti-inflammatory cytokine IL-10 have shown that carrying genotypes GA and GG of rs1554286 IL10 is a predictor of anxiety (HR 1.85, p = 0.019) in early-stage breast cancer patients in China, which could help identify patients at high risk for psychological problems." (PMID 37510364, 2023). "However, the presence of intratumoral IL10+ Bregs is a poor prognostic feature in breast cancer." (PMID 37887534, 2023). "The importance of HIIT for breast cancer patients may stem in part from its anti‐inflammatory mechanisms, achieved through the down‐regulation of pro‐inflammatory factors such as IL‐6, and the up‐regulation of anti‐inflammatory factors like IL‐10 and TNF‐α." (PMID 37587859, 2023). "Our study reveals that the levels of sPD-L1 or IL-10 in the serum or PD-1+ Bregs in the PBMCs of breast cancer patients might be predictors for immunotherapy, and combination PD-L1 antagonist and CD40 agonist Abs might be a more efficient immunotherapy for TNBC." (PMID 35935985, 2022). "In addition, we have recently shown an immunomodulatory effect of this peptide, which significantly decreased the expression of IL-1β in tumor and lung tissues and increased the levels of IL-10 anti-inflammatory cytokines in the primary tumor of 4T1 mouse mammary carcinoma as observed in other AMPs." (PMID 35601827, 2022).
breast cancer (continued). "In addition, we measured serum IL10 in serum from patients with breast cancer and healthy subjects." (PMID 33500726, 2021). "Moreover, serum IL10 shows a positive correlation with serum CCL16 in patients with breast cancer." (PMID 33500726, 2021). "Hence, higher levels of IL10 may increase tumor immune escape and this hypothesis is consistent with the observation of increased IL10 concentration in serum of breast cancer patients, particularly in case of metastatic disease." (PMID 32300557, 2020). "The fact that IL10 expression was strongly induced in NF and CAF co-cultured with BC-PBMC indicates that BC-PBMC could be instrumental in the induction of immune tolerance against breast cancer cells and thus a suppression of an anti-tumoral immune response by upregulating IL10." (PMID 33396463, 2020). "Similarly, IL-10 produced by TAMs can induce breast cancer chemoresistance." (PMID 31485295, 2019). "Similar to IL-10, IL-6 may act to promote or suppress breast cancer." (PMID 30640711, 2019). "In the context of breast cancer, IL-10 may act as a two-edged sword." (PMID 30947706, 2019). "The possible TAMs-modulated drug resistance mechanism involved may be associated with elevation of bcl-2 gene expression and up-regulation of STAT3 signaling in tumor cells, forming IL-10/STAT3/bcl-2 signaling axis accounting for chemoresistance of breast cancer." (PMID 30175384, 2018). "However, curcumin pre-treatment for 5 days in cisplatin-treated rats significantly reduced the levels of TNF-α (p < 0.001), IL-6 (p < 0.01), and IL-8 (p < 0.05) whereas significantly improved the level of IL-10 (p < 0.001) as compared to cisplatin-treated breast cancer rats." (PMID 28420987, 2017). "IL-10 is a multifunctional cytokine with both immunosuppressive and antiangiogenic functions, which may play varied roles in the pathogenesis and development of breast cancer." (PMID 20553628, 2010). "Breast cancer microenvironments are enriched with inhibitory cytokines (TGF-β, IL-10), myeloid-derived suppressor cells (MDSCs), and cancer-associated fibroblasts (CAFs), which collectively limit immune infiltration and promote exhaustion." (PMID 41348261, 2025). "By increasing Treg numbers, IL-10 further reduces the effectiveness of cytotoxic T-cells (CD8 + T-cells) and helper T-cells (CD4 + T-cells), weakening the immune response against breast cancer cells." (PMID 40486614, 2025). "We focused on IL-2, IL-6, IL-10, and TNF-α due to their well-documented relevance in breast cancer immunobiology, as reported in previous studies." (PMID 40869161, 2025). "The polarized M2 macrophages secrete vascular endothelial growth factor (VEGFA) and immunosuppressive factors such as interleukin-10 (IL-10), thereby remodeling the pulmonary PMN and facilitating breast cancer cell colonization in the lung." (PMID 40564894, 2025). "In postmenopausal women with early breast cancer, longitudinal studies reported short-term increases of 15–48% in IL-6, IL-8, IFN-γ, TNF-α, and IL-10 after adjuvant chemotherapy, returning toward baseline within 6–12 months." (PMID 41153842, 2025). "In liver (LIHC) and breast cancers (BRCA), both IL-10 and TGF-β1 family molecules show increased expression in tumor tissues, indicating a coordinated activation of the immunosuppressive microenvironment." (PMID 41438510, 2025). "For instance, in the breast cancer mouse model, blocking IL-10 signal transduction greatly enhances chemotherapy effectiveness because the TAM is the primary source of IL-10." (PMID 40422244, 2025). "Changes in anti-inflammatory cytokines such as IL-10 and IFN-γ were limited, consistent with two prior studies focused on breast cancer patients." (PMID 40895542, 2025). "Communication between macrophages and MDSCs further subverts tumor immunity by enhancing production of IL-10 by MDSC and diminishing IL-10 production derived from macrophages in spontaneously metastatic 4T1 mouse mammary cancer." (PMID 38935134, 2024).